CCNE1 (cyclin E1)
Diseases named in the same sentence as CCNE1 in open-access papers (continued):
Sharing a sentence is not in itself a finding about the gene and the disease.
cancer (continued). "As both low levels of BRCA1 and BRCA1 methylation are very common to BLBC38, and our data demonstrate elevated cyclin E1 in the BRCA1 methylated BLBC, a rational ongoing area of investigation is CDK2 inhibition to sensitize BRCA1 methylated or deficient cancers to PARP inhibitors." (PMID 34465787, 2021). "There is much less information of PRMT5 and Cyclin E1, which may be due to the higher prevalence of cancers with Cyclin D1 than with Cyclin E1 overexpression." (PMID 34168658, 2021). "Since cyclin E1/CDK2 protects cells from DNA damage and cyclin E1 is elevated in BRCA1 mutant cancers, we hypothesized that CDK2 inhibition would sensitize these cancers to PARP inhibition." (PMID 34465787, 2021). "In addition, a previous study reported that cyclin E1-driven EOC was associated with activated polyamine synthesis and decreased cancer immunity." (PMID 34134729, 2021). "Furthermore, alterations in the associated genes (CDK-1, CDK-4, CCNE1, CDKN2A, RBI, NCAPG, AURKA, and CCND2) were determined in five CRC studies (CRC, TCGA, Firehose, CRC, TCGA, Nature, CRC, Pan-Cancer, MSKCC and CPTAC-2)." (PMID 33732631, 2021). "A number of studies have shown that CCNE1 is abnormally expressed in a variety of malignant tumors." (PMID 33791304, 2021). "ATR inhibition is lethal with numerous cancer-associated changes, including oncogenic stress (oncogenic RAS mutations, MYC and G1/S-specific cyclin-E1 (CCNE1) overexpression), deficiencies in DNA repair (TTP53, BRCA1/2, partner and localizer of BRCA2 (PALB2) and ATM loss) and other defects." (PMID 32316968, 2020). "To test whether high expression levels of Cyclin E1 influenced DNA replication kinetics and sensitivity of cancer cells to ATR and WEE1 inhibitor, we aimed to downregulate Cyclin E1 expression in TNBC cancer cells." (PMID 33028815, 2020). "Increasing evidence indicates cyclin A2, cyclin D1 and cyclin E1 are positively correlated with the development of chemotherapy resistance, while the knockdown or depletion of these proteins inhibits cancer cell proliferation and promotes apoptosis, increasing sensitivity to chemotherapeutic drugs." (PMID 33292277, 2020). "Furthermore, in the study of Xue and colleagues, CCNE1 3′UTR lengthening was observed to be recurrently detected in six cancer types including BC." (PMID 32503257, 2020). "Consistently, CCNE1 amplification has been associated with WGD in TCGA pan-cancer analyses and CCNE1 overexpression has been shown to induce CIN phenotypes in various cancer cells." (PMID 33257699, 2020). "Previous studies have shown that the upregulation of CCNE1 could contribute to cancer development or tumorigenesis in many cancers, and CCNE1 could serve as a reliable independent prognostic marker." (PMID 32962636, 2020). "As well as its role in the normal cell cycle, cyclin E1 is a potent oncogene: it is overexpressed or amplified in multiple malignancies, expression correlates with decreased survival and transgenic mice with deregulated cyclin E1 expression develop carcinomas." (PMID 32823571, 2020). "In addition, these studies reveal that Cyclin E1 is an upstream activator of FOXM1 expression in human cancers, including HGSC." (PMID 30795624, 2019).
cancer (continued). "As polyamine was reported to mediate microenvironment and cancer immunity, we queried the expressions of CCNE1 and polyamine genes again immune infiltrates and found that the CCNE1 expression was significantly correlated with macrophage and neutrophil infiltration." (PMID 31657115, 2019). "DAB2 and CCNE1 are a tumor suppressor gene and oncogene pair normally involved in strong stabilizing molecular interaction negative feedback loops, and it is these interactions that are sufficiently perturbed during cancer development." (PMID 30944378, 2019). "The top 1 network in the spleens of A.SW mice was categorized as “Cell Cycle,” “Reproductive System Development and Function,” and “Cancer,” including down-regulated genes: cyclin family (Ccne1, Ccnb1, and Ccnb2) and cell division cycle family (Cdc20, Cdc25b, and Cdc25c)." (PMID 30941144, 2019). "Targeting CDK2 has thus far been the only targeting approach for CCNE1 amplified cancer." (PMID 31313989, 2019). "Hence, several alternative approaches have been proposed to decrease the viability of the CCNE1-amplified subset of cancer cells, including the use of several CDK inhibitors and the proteasome inhibitor Bortezomib." (PMID 29899826, 2018). "CCNE1 located at 19q12 is frequently amplified in EC and a target for anti-cancer therapy." (PMID 27582547, 2017). "Recently, CDK2, CCNE1 genes were described as cancer prognostic factors." (PMID 28042959, 2017). "In addition, there is a significant increase in the activity of the CDK2, CCNE1 effector circuit as cancer stage progresses." (PMID 28042959, 2017). "A total of three differentially hypermethylated genes (CCNE1, PON3, and CCNDBP1) and two differentially hypomethylated genes (DDX43 and CHL1) were selected for the validation based on their β-value and association with CRC as well as other cancers." (PMID 28243201, 2017). "In univariate Kaplan–Meier analysis and univariate Cox regression analysis, patients with high Cyclin E1 expressing carcinomas had significantly shorter overall survival time than patients with low Cyclin E1 expression (log-rank test, p = 0.017; HR = 1.59, 95%CI, 1.09–2.3)." (PMID 27582547, 2017). "Cyclin E1 immunohistochemical analysis was possible in 412 carcinomas." (PMID 27582547, 2017). "Many cancers typically overexpress cyclin E1, which is also proved in the MCF-7 cell line." (PMID 27483236, 2016). "The high degree of sequence homology between cyclin E1 and E2 suggests that many of their functions may be interchangeable, but recent publications in cancer and liver biology show that these proteins have unique regulation and function." (PMID 25741376, 2015). "Future studies should carefully differentiate cyclin E1 and E2 and their isoforms, especially since each protein has unique expression patterns and their expression has distinct correlation with patient outcome in cancer." (PMID 25741376, 2015). "CDK2 and CCNE1 were increased in carcinomas showing that these use the opposite way to control RB1." (PMID 26008974, 2015). "In contrast to CDKi, Bortezomib primarily affects the homologous repair system itself, resulting in synthetic lethality in CCNE1-amplified cancer cells: a genome-wide shRNA screen in 102 cancer cell lines revealed that BRCA1 was specifically required in CCNE1-amplified cell lines." (PMID 24624361, 2014). "This suggests that high levels of cyclin E1 confer an added advantage to BRCA-proficient cancers." (PMID 24624361, 2014). "As discussed for CDKi, specific selection of patients with CCNE1-amplified cancers for Bortezomib treatment may further increase the response rate." (PMID 24624361, 2014).
cancer (continued). "However, the mechanisms by which cyclin D1 and cyclin E1 are upregulated in cancer cells remain to be fully elucidated." (PMID 23383003, 2013). "Consistent with this hypothesis, we observed that cancer cells harbouring 19q12 amplification require the expression of not only CCNE1, but also PLEKHF1, POP4 and TSHZ3 for their survival." (PMID 22433433, 2012). "Given that CCNE1 silencing in cancer cells harbouring CCNE1 gene amplification leads to G1 arrest, we tested whether these cells would be dependent on CDK2 expression and kinase activity for their survival." (PMID 22433433, 2012). "Oncogenes such as MYC, AKT1, AKT2, cyclins CCNA2, CCNB1, CCNB2, CCNE1, CCNE2 and cyclin-dependent kinases CDK1 and CDK4, which were upregulated under androgen treatment, exhibited a significantly reduced expression following PVT1 knockdown, thereby modulating cancer-associated oncogenic pathways." (PMID 41792045, 2026). "However, in cancer, aberrant CCNE1 expression can lead to uncontrolled proliferation." (PMID 39591374, 2024). "CCNE1 overexpression may influence the response to various cancer treatments." (PMID 39591374, 2024). "RAPGEF3 has been implicated in cancer progression through various downstream signals, e.g. RAPGEF3 promotes cancer cell proliferation and/or suppresses apoptosis via Rap1/Akt/CREB signaling, Rap1/B-Raf/ERK and mTOR signaling or acting synergistically with PDE4 to promote the Cyclin E1-Cnx43 axis." (PMID 39687207, 2024). "Moreover, transgenic mice with deregulated Cyclin E1 expression developed carcinomas." (PMID 39201710, 2024). "In the pan-cancer analysis, a decreased probability of overall survival (OS) and disease-specific survival (DSS) was found in amplified tumors in comparison with non-amplified ones, with EGFR, CDK4, MDM2, KRAS, and CCNE1-amplified tumors being those associated with a worse prognosis." (PMID 36980521, 2023). "Furthermore, to assess whether CCNE1 interference has a synergistic effect with anti-cancer agents such as cisplatin (60 μg/kg), a combination in vivo assay was conducted." (PMID 34070839, 2021). "Importantly, we observed one cancer cell line in which elevated cyclin E1 caused by knockdown of FBXW7 did not appear to activate CDK2 (as measured by pNPM)." (PMID 32076484, 2020). "Because the amplification of CCNE1 leads to increased cell proliferation, it could just be an advantageous trait gained by cancer cells to help them survive in general and would then allow cells that develop resistance to chemotherapy to proliferate uninhibited." (PMID 33182737, 2020). "Potent CDK2 inhibitors might target certain cancers in which CCNE1 is amplified." (PMID 30472117, 2019). "However, cyclin E1 is aberrantly overexpressed in many human cancers." (PMID 29261144, 2017). "Thus, Nault and coworkers have reported in some of these patients the clonal integration of adeno-associated virus type 2 (AAV2) at the level of some cancer driver genes, including CCNA2 (cyclin 2), TERT, CCNE1 (cyclin E1), TNSF10 and KMT2B, inducing overexpression of the target genes." (PMID 28930164, 2017). "Similar to retrovirus, HBV genes could insert into host cancer genes such as those encoding telomerase reverse transcriptase (TERT), mixed-lineage leukaemia protein 4 (MLL4) and cyclin E1 (CCNE1) causing oncogenesis, and could exert effects on cell functions persistently." (PMID 28640739, 2017). "Hence, the RB pathway directly controls BRCA expression via regulation of E2F activity, and targeting of cancer-specific RB pathway lesions, such as CCNE1, may result in downregulation of BRCA gene expression." (PMID 24624361, 2014). "Besides MYC and CCNE1, there are multiple genes in these regions, which could contribute to a growth advantage for the cancer cell." (PMID 21781349, 2011). "First, we establish CCNE1 as a subtype-specific prognostic determinant in TNBC, contrasting with prior studies that primarily focused on its pan-cancer roles." (PMID 40346052, 2025).
cancer (continued). "ILF3 is known to stabilize mRNAs of proteins like Cyclin E1, ERp57, and SGOC, which promote the proliferation and metastasis of cancers, including hepatocellular, renal, and CRC." (PMID 40234937, 2025). "Cyclin E1, the protein product of CCNE1, which can stimulate the progression of S phase, is overexpressed in high proliferation cancer cells." (PMID 39318358, 2024). "The efficacy of this agent in preclinical models of both CCNE1-amplified and CDK4/6i–resistant cancers was encouraging and supported the rationale for targeting CDK2 in cancer, but its clinical development has been discontinued." (PMID 38047585, 2024). "In order to maintain cancer cell proliferation, HLXB9 upregulates genes that are involved in the G1-S transition of the cell cycle, such as Cyclin E1 (CCNE1) and Cyclin E2 (CCNE2)." (PMID 39239563, 2024). "In cancer, upregulated oncoproteins KRAS, MYC, CCNE1, etc. act as primary sources of replicative stress, while also impairing the cell’s ability to adequately respond to such stress." (PMID 38669256, 2024). "Erik’s report illustrate the complex nature of cancer cell cycles, genes (CDK4, CDK6, CCND1, CDK2, and CCNE1) that regulate the G1/S transition yield particularly variant vulnerabilities in different cancer cell." (PMID 38582921, 2024). "The LINC00355/miR‐195/CCNE1 mRNA axis was shown to inhibit G1 arrest and promote cell cycle progression in two LUAD cancer cell lines (A549 and H1299)." (PMID 38125763, 2023). "LINC00355 induces chemotherapy resistance in cancer cells by regulating five downstream genes, namely HMGA2, ABCB1, ITGA2, WNT10B, and CCNE1 genes." (PMID 38125763, 2023). "The expression of certain cell cycle genes (CCNB1, CCNE1, CCNE2, and FOXM1) was race-dependent in several cancer types and correlated with significant survival differences." (PMID 37345032, 2023). "proved the important role of lncRNAs ELDR in cancer, interacted with RNA binding protein ILF3, and enhanced ILF3-Cyclin E1 signaling to enhance cancer growth." (PMID 37359524, 2023). "Only a small subset of these genes was differentially expressed in multiple carcinomas, including genes involved in cell cycle progression such as CCNB1, CCNE1, CCNE2, and FOXM1." (PMID 37345032, 2023). "The findings discovered recurrent HBV integration events at the known and potential cancer-related TERT, MLL4, and CCNE1 genes, which demonstrated increased gene expression in HCC compared to normal tissue." (PMID 35518785, 2022). "Stratifying patients according to the combined expression of CCNE1 and CDC25A revealed the expected pattern across most types of cancer: TTLL11 is downregulated in tumors with high expression of at least one of the two potential TTLL11 upstream regulators." (PMID 36414642, 2022).
cancer (continued). "Integrations occurred in the known cancer driver genes CCNA2, (four cases), TERT (one case), CCNE1 (three cases), TNFSF10 (two cases) and KMT2B (one case), leading to overexpression of the target genes." (PMID 36316711, 2022). "Taken together, inactivation of Ccne1 after HCC initiation exhibited a lower reaction to DNA damage and reduced hallmarks of cancer progression, such as stemness and invasion." (PMID 34830835, 2021). "Several of these events involve known cancer-related oncogenes, such as YWHAZ (8q22.3), MDM2 (12q15), and CCNE1 (19q12)." (PMID 33397444, 2021). "We observed that BRCA1/2 gene alterations were mutually exclusive with amplification of all the oncogenes examined in the breast (CCND1, CCNE1 and CDC6) and ovarian (CCND1, CCNE1 and BRAF) cancer cohorts." (PMID 34389725, 2021). "Other cancer-related genes with recurrent insertions within gene boundaries are KMT2B (n = 4, three in coding exons) and CCNE1 (n = 2, all intronic), both at chromosome 19q." (PMID 34824211, 2021). "To explore the transcription levels of CCNE1, E2F1 in other types of cancer, we profiled the tissue-wise expression of these genes in different cancer types by GEPIA 2 based on TCGA datasets." (PMID 33613291, 2021). "The third reported mechanism is the insertional mutagenesis, which can integrate the viral DNA into host cancer genes (telomerase reverse transcriptase (TERT), myeloid/lymphoid or mixed-lineage leukemia 4 (MLL4), and cyclin E1 (CCNE1))." (PMID 31947702, 2020). "Genomic amplification of CCNE1 occurs in many cancer types and is an established driver of CIN, cellular transformation and cancer progression." (PMID 32106628, 2020). "Overall, these results suggested that SP1 activated ABCC1 and stimulated the expression of the CCNE1, ERF, and MYB genes, which have been shown to be related to chemoresistance and cancer relapse." (PMID 31118037, 2019). "SPOP directly interacts with CYCLIN E1, poly-ubiquitinates CYCLIN E1 in vivo and in vitro, and represses cancer-related phenotypes induced by CYCLIN E1 expression." (PMID 30237511, 2019). "To further study its role in liver malignancy, we examined the expression of several cyclin family members in large scale cancer datasets provided by TCGA, including CCNA1, CCND1, and CCNE1." (PMID 31349793, 2019). "We identified 156 focal amplifications and 69 focal deletions, in well-known oncogenes, such as ERBB2, CCNE1, KRAS, MYC, EGFR, and CDK6, and cancer-related genes such as GATA4, GATA6, CD44 and ZNF217." (PMID 31570735, 2019). "Disappearance of indirect connections between STIL and CDK1 can be interpreted as loosening the control over several important cyclins (CCNA2 and CCNE1) and the key cell cycle protein CDK1 in cancer." (PMID 29370181, 2018). "First, the number of RS1 rearrangements was higher in CCNA2-activated HCC (median = 269) than in CCNE1-activated HCC and BRCA1-altered breast and ovarian cancers." (PMID 30531861, 2018). "Second, tandem duplications were larger in CCNE1-activated HCC (median = 39 kb) than in CCNA2-activated HCC (22 kb), and smaller in BRCA1-altered breast (9 kb) and ovarian (10 kb) cancers." (PMID 30531861, 2018). "Of note, both in the pan-cancer and in the BC datasets, CCNE1/RB1 performed better than CCNE1 or RB1 alone in predicting palbociclib de novo resistance." (PMID 30511015, 2018). "Instead, we observed that several indirect interactions disappear in the “cancer” network, namely three indirect regulations connecting STIL protein to CCNA2, CCNE1 and CDK1." (PMID 29370181, 2018). "Overexpression of cyclin-dependent kinases (CDKs) and cyclin proteins (CCND1, CCNE1, and CCNB1) are found in many human cancers." (PMID 28466007, 2017).